CLDN4 (claudin 4)
Diseases named in the same sentence as CLDN4 in open-access papers (continued):
Sharing a sentence is not in itself a finding about the gene and the disease.
breast carcinoma (continued). "In the present study, we demonstrated that CLDN4 accelerates breast cancer progression in vitro and in vivo." (PMID 37059993, 2023). "Tumor budding, small clusters of cancer cells, was hindered in T47D:CLDN4–/– xenografts compared with T47D xenografts, further indicating that CLDN4 functions as a tumor promoter in breast cancer cells." (PMID 37059993, 2023). "CPE is cytolytic due to its ability to form pores in cellular membranes, and CPE treatment in breast cancer cells have shown promising results due to the high expression of Claudin-4." (PMID 36077843, 2022). "Of the 27 Claudins, Claudin-4 shows a significant change in tumors and is overexpressed in primary breast cancers." (PMID 36077843, 2022). "The C-terminal fragment of CPE (c-CPE) provides a less toxic alternative for drug delivery into breast cancer cells, particularly metastatic tumors in the brain, especially as Claudin-4 expression in the central nervous system (CNS) is low." (PMID 36077843, 2022). "The negligible presence of Claudin-4 in normal brain cancer cells and the high abundance of Claudin-4 in breast cancer cells metastasized to the brain, allow for the targeted binding of CPE to tumor cells in the brain." (PMID 36077843, 2022). "Recombinant c-CPE-proteins can thus be developed as TJ modulators for enhanced delivery of drugs into breast cancer and brain metastatic cells overexpressing Claudin-4." (PMID 36077843, 2022). "The expression of Claudin-4 (CLDN4) is positively correlated with PAK4 in breast cancer and PAK4 induces CCAAT/enhancer binding protein β (CEBPB) activation, resulting in upregulation of CLDN4." (PMID 36105226, 2022). "We previously radiolabeled a cCPE.GST peptide with 111In to enable SPECT imaging of claudin-4 in mouse models of breast cancer." (PMID 32414951, 2020). "This study confirmed the ability of [111In]In-cCPE.GST to delineate claudin-4 expression both in overt mammary tumors and in aplastic lesions in genetically engineered BALB/neuT mice." (PMID 32414951, 2020). "Overexpression of claudin-4 significantly reduces the invasive potential and clonogenic activity, as well as pulmonary metastasis, in human pancreatic cancer cells, breast cancer cells, and clear cell renal cell carcinoma." (PMID 31717460, 2019). "Previous studies have shown that ZO-3 and Claudin-4 are expressed in mammary epithelial cells or luminal subtypes of breast cancer such as MCF7." (PMID 29190905, 2017). "Claudin-low breast cancer is a relatively rare breast cancer subtype where the tumor cells possess mesenchymal characteristics as well as very low levels of claudin-3 (Cldn3), Cldn4 and Cdln7; properties that were observed in the RSTs." (PMID 28423599, 2017). "Previous studies have elaborated the expression of CLDN3 and CLDN4 effect on the metastatic ability of breast cancer cells." (PMID 29221203, 2017). "Western blot analysis revealed a possible correlation between claudin-4 and -6 expression in breast cancer cell lines and tumor aggressiveness, with protein levels correlating with the ability to form vascular channels." (PMID 25871476, 2015). "Specific inhibition of claudin-4 using mAbs led to complete inhibition of vascular channel formation in aggressive breast cancer cells, while this effect was minimal using claudin-6 blocking antibody." (PMID 25871476, 2015). "We demonstrate that claudin-4 or claudin-6 blocking antibodies have different effects on VM formation in aggressive breast cancer cells in vitro." (PMID 25871476, 2015). "In our study, we identified abnormal overexpression of two claudin members, claudin-4 and -6, in aggressive breast cancer cells." (PMID 25871476, 2015). "Claudin-4 is frequently expressed in primary breast cancers but especially in their metastases and is thereby an attractive membrane bound molecular imaging and drug target." (PMID 25417118, 2014). "Claudin-4 is a membrane bound marker and is upregulated in many tumors, including breast cancer and its metastases." (PMID 25417118, 2014).
breast carcinoma (continued). "The expression of other claudin family members, such as CLDN1 in podocyte and breast cancer and CLDN4 in bladder cancer, has also been reported to be regulated through promoter hypermethylation." (PMID 25277196, 2014). "Because T47D breast cancer cells are known to express high levels of claudin-4, we expected more peptide to be bound to their surface compared to the 21MT1 cells." (PMID 23521713, 2013). "In the present study, we found upregulation of claudin-4 in breast carcinoma effusions compared to primary carcinomas, suggesting that members of this family are upregulated at this anatomic site in multiple epithelial malignancies." (PMID 19680458, 2010). "There is also interest in CLDN4 and CLDN9 as markers of drug resistance; for instance, CLDN9 upregulation in breast cancer was associated with chemotherapy failure, suggesting that targeting CLDN9 or its pathway could resensitize tumors to treatment." (PMID 40687428, 2025). "Likewise, in breast cancer, cell proliferation, migration, and tumor growth are enhanced via CLDN4-adhesion signaling, which works through interacting with LXRβ by targeting the AKT phosphorylation site S432 in LXRβ." (PMID 38731853, 2024). "Patients with breast carcinomas showing high claudin-4 protein expression may benefit from anti-claudin-4 antibody treatment as part of the treatment protocol." (PMID 39687048, 2024). "To evaluate whether the CLDN4 signaling drives breast cancer metabolism and progression via LXRβ, we generated T47D:CLDN4–/–:LXRβ–/– (hereafter designated as "T47D:dKO"), T47D:dKO:CLDN4, and T47D:dKO:CLDN4:LXRβ cells." (PMID 37059993, 2023). "Taken collectively with our data showing that the level of LXRβ protein in T47D:dKO:CLDN4:LXRβS432A cells was similar to that in T47D:dKO:CLDN4:LXRβ cells, these results revealed that LXRβS432A is critical for the CLDN4-provoked breast cancer metabolism and advancement." (PMID 37059993, 2023). "In addition, using T47D:CLDN4–/– and MDA-MB-231:CLDN4 xenografts, it was shown that CLDN4 promotes the tumor growth and cell proliferation of breast cancer cells in vivo." (PMID 37059993, 2023). "Moreover, by immunohistochemistry and semi-quantification, we verified the clinicopathological significance of CLDN4 and the nuclear receptor LXRβ (liver X receptor β) expression in breast cancer tissues from 187 patients." (PMID 37059993, 2023). "By generating a number of knockout and rescued human breast cell lines and comparing their phenotypes, we determined whether and how CLDN4 affected breast cancer progression in vitro and in vivo." (PMID 37059993, 2023). "CTC count and classification and the expression level of Claudin-4 may be used for the early diagnosis and prognosis of breast cancer." (PMID 37465316, 2023). "Epithelial markers (e.g., GRHL2, CLDN4 and E-cadherin) are lost in basal B breast cancer cells as compared to the luminal and basal A subtype and we examined whether EHF expression followed this pattern." (PMID 36691073, 2023). "Furthermore, we have very recently demonstrated that aberrant CLDN4/SFK signaling drives breast cancer metabolism and progression via Liver X receptor β." (PMID 37443730, 2023). "Taken together, we hypothesized that the CLDN4 signaling might regulate breast cancer progression by regulating the nuclear receptor activity in a similar mechanism to CLDN6 in endometrial cancer." (PMID 37059993, 2023). "Claudin-4•c-CPE interactions can also aid the creation of technologies that modify TJs containing Claudins for improved metastatic brain cancer treatment from primary cancers such as breast cancers that overexpress Claudin-4." (PMID 36077843, 2022). "c-CPE also shows Claudin-4 dependence in mediating its cytotoxicity in breast cancer cells." (PMID 36077843, 2022). "Moreover, silencing of claudin-4 in MCF-7 breast cancer cells resulted in a significant reduction of cell migration and played a crucial role in tumor metastasis." (PMID 34638619, 2021).
breast carcinoma (continued). "Studies have shown that CLDN4 can be a useful prognostic marker in breast cancer." (PMID 33801373, 2021). "PAK4-mediated CEBPB activation upregulates CLDN4 expression to promote cell migration and invasion in breast cancer, thus, PAK4/CEBPB/CLDN4 may be a potential therapeutic target in breast cancer treatment." (PMID 34490085, 2021). "One study based on breast cancer found that CEBPB was a novel transcriptional regulator of CLDN4." (PMID 32677948, 2020). "Claudin-4 and 14-3-3δ/ζ, are of particular interest in the breast cancer landscape." (PMID 28881568, 2017). "In addition to tight junctions, claudin 4 has been shown to be localized in cellular projections of breast cancer cells, where it promotes cellular motility in a wound-healing model." (PMID 27241529, 2016). "Collectively, these results indicate that claudin-4 may play a critical role in VM in human breast cancer cells, opening new opportunities to improve aggressive breast cancer therapy." (PMID 25871476, 2015). "Taken together, these results indicate that claudin-4 may be critical for VM formation in breast cancer cell lines." (PMID 25871476, 2015). "Since the association between claudin-4 expression and HER-2 overexpression had previously been reported in breast carcinomas, we investigated whether this association would be confirmed in our set of non-nodular breast lesions." (PMID 23657508, 2013). "To determine whether claudin could be found within cellular projections in cells that lack the ability to form tight junction structures, we examined localization of claudin-4 in breast cancer cells." (PMID 23521713, 2013). "However, recent studies have shown that the distinct prognostic significance of claudin-3 or claudin-4 is dependent on the subtype of breast cancer." (PMID 24009024, 2013). "High levels of CLDN4 have been reported in basal-like breast cancers." (PMID 23236365, 2012). "However, CLDN4 was highly positive in normal epithelial cells and was decreased or absent in 17 out of 21 ductal carcinoma grade 1, in special types of breast carcinoma (mucinous, papillary, tubular) and in areas of apocrine metaplasia." (PMID 15743508, 2005). "The mRNA expression of different CLDNs in a large number of special-type breast carcinomas and tumours of different grades requires investigation so that the decrease in CLDN4 expression in special-type breast carcinomas and IDCs of grade 1 can be unequivocally confirmed." (PMID 15743508, 2005). "Increased claudin-4 expression may have a role in breast cancer progression." (PMID 39687048, 2024). "However, the relationship between CTCs and Claudin-4 in breast cancer is unclear." (PMID 37465316, 2023). "Therefore, both Claudin-4 and CTC might be used to evaluate the prognosis and recurrence risk of patients with breast cancer." (PMID 37465316, 2023). "We then verified whether CLDN4 also promoted breast cancer progression in vivo." (PMID 37059993, 2023). "While enhanced expression of CLDN4 in luminal breast cancers was linked to poor clinical outcomes, contrastingly, overexpression of CLDN4 in TNBC was associated with favorable outcomes in which tumors that overexpressed CLDN4 displayed a less aggressive phenotype." (PMID 33801373, 2021). "Breast cancer cell lines reflective of the CL subtype were also found to express low or absent levels of the epithelial cell-cell adhesion proteins examined (E-cadherin, claudin 3, claudin 4 and claudin 7) and markers of breast luminal epithelial cell differentiation (ER, PR and HER-2)." (PMID 28045912, 2017). "Thus, further studies investigating the overexpression of claudin-4 in aggressive breast cancer cells may help to elucidate the molecular mechanisms underlying the channel-forming ability of these highly aggressive tumor cells." (PMID 25871476, 2015).
breast carcinoma (continued). "Single agent treatment with a human monoclonal anti-CLDN4 antibody (4D3), resulted in moderate effects on in vitro cell growth inhibition across bladder, CRC, gastric, pancreatic or breast cancer cells." (PMID 38371623, 2024). "To date, targeting CLDN4 has been explored in pancreatic, ovarian, gastric, CRC, bladder or breast cancer mouse models." (PMID 38371623, 2024). "We also showed that CLDN4 activates SFK and the downstream AKT in breast cancer cells in the EC2- and Y197-dependent manners, leading to promote their cell proliferation." (PMID 37059993, 2023). "Our data do confirm CLDN4 as a direct target gene with GRHL2-binding in the promoter region and transcriptional suppression in response to GRHL2 depletion in luminal breast cancer cells." (PMID 36691073, 2023). "The CLDN4-triggered cell proliferation was completely prevented in MDA-MB-231:CLDN4ΔC cells, further showing the importance of CLDN4-C in breast cancer progression." (PMID 37059993, 2023). "It has been reported that BHLHE40 can promote SNAI1 and SNAI2 expression and inhibit the expression of CLDN1, CLDN4, and CDH2 in breast cancer, promoting the migration and invasion of tumor cells." (PMID 37377917, 2023). "The second extracellular domain and the carboxy-terminal Y197 of CLDN4 were required to activate Src-family kinases (SFKs) and the downstream AKT in breast cancer cells to promote their proliferation." (PMID 37059993, 2023). "The Multivariate COX regression model showed that Claudin-4, lymph node metastasis, and CTC classification E/M-CTC and M-CTC were adverse factors for the prognosis of breast cancer patients." (PMID 37465316, 2023). "We also demonstrate that the CLDN4 signaling activates SFK/AKT and targets LXRβS432, resulting in stimulation of the LXRβ activity and malignant behaviors in breast cancer cells." (PMID 37059993, 2023). "The treatment of breast cancer cells and brain metastasis with c-CPE in its various forms is effective because Claudin-4 is steadily expressed in those cancers." (PMID 36077843, 2022). "The plakoglobin (JUP), KRT8, KRT18, KRT19, CLDN4, and EPCAM, which their role in breast cancer metastasis was demonstrated in previous studies, are EMT markers." (PMID 34801010, 2021). "The finding of absent expression of claudin 4 in apocrine carcinoma, with its known good prognosis, is also consistent with the reported association between claudin 4 over-expression and poor prognosis and increased incidence of axillary and distant metastasis in breast carcinoma." (PMID 31044387, 2020). "It has been reported that recovery of various claudin proteins expression, such as CLDN3, CLDN4, and CLDN7, can reduce the malignant behavior of cancer cells and reduce the invasiveness in breast cancer." (PMID 29221203, 2017). "The claudin-low subtype is a recently identified molecular subtype of human breast cancer characterized by low expression of tight junction and adherens genes including CLDN3, CLDN4, CLDN7 and CDH1." (PMID 24009024, 2013). "For instance, a Japanese group showed that the combination of claudin-4 and E-cadherin expression called CURIO accurately predicts relapse-free survival in breast cancer." (PMID 24009024, 2013). "Among EMT-related genes, direct regulation of CLDN4 is corroborated but several targets identified in other cells (including CDH1 and ZEB1) are ruled out by both ChIP- and Bru-seq as being directly controlled by GRHL2 in luminal breast cancer cells." (PMID 36691073, 2023). "Hence, these results indicated that the CLDN4 signaling activates SFK/AKT and accelerates breast cancer progression in the EC2- and the C-terminal Y197-dependent manners." (PMID 37059993, 2023). "In contrast, CLDN3, CLDN4 and CLDN5 appear to be overexpressed in breast cancers." (PMID 38137355, 2023). "Along this line, clinicopathological analysis using expression levels of either CLDN4 or LXRβ does not seem to be enough to predict a prognosis in breast cancer, especially in TNBC." (PMID 37059993, 2023).
breast carcinoma (continued). "Using Claudin-4 as a target for fluorescent molecules, c-CPE bound to NP (c-CPE NP) can be further localized and administered intraperitoneally (IP) in breast cancer cells to significantly lessen systemic toxicity than with the same dose administered intravenously." (PMID 36077843, 2022). "The top differentially expressed genes (unadjusted P ≤ .001) were all upregulated and included KIFC1 (OMIM 603763), FAM83D (OMIM 618380), UBE2C (OMIM 605574), CLDN4 (OMIM 602909), GRB7 (OMIM 601522), and PKMYT1 (OMIM 602474), each of which have previously reported roles in breast cancer progression." (PMID 34714340, 2021). "Third, the VM formation of breast cancer involves signaling pathways and some factors related to tumor cell migration and invasion, including Nodal signaling pathway, heat shock protein 27 pathway, AURKA protein kinase, IL-8 and Claudin-4." (PMID 28915600, 2017). "The results prompted us to conduct a preliminary functional analysis to investigate the effect of specifically inhibiting or overexpressing claudin-4 in aggressive and non-aggressive breast cancer cells, respectively, on VM." (PMID 25871476, 2015). "The previously discovered role of claudin-3 and claudin-4 in cell motility and increased MMP-2 activity suggests that this may be yet another metastasis-promoting molecule in breast carcinoma effusions." (PMID 19680458, 2010). "CLDN4 was absent or its expression was decreased in the seven special-type breast carcinomas (mucinous, tubular, papillary) but it was present in the normal tissue surrounding these tumours." (PMID 15743508, 2005). "No studies to date have reported decreased expression of CLDN4 in grade 1 breast carcinomas, in special types of breast tumour, or in apocrine metaplasia compared with normal epithelium, as were observed in our study." (PMID 15743508, 2005). "The survival time of the Claudin-4 high-expression group was significantly lower than that of the low-expression group, and a multivariate COX regression model was established to find that high expression of Claudin-4 was an independent factor affecting the poor prognosis of breast cancer." (PMID 37465316, 2023). "On Kaplan–Meier plots for 187 breast cancer cases, the overall survival rate in the "CLDN4-high/LXRβ-high" group was slightly lower than that in the "CLDN4-low and/or LXRβ-low" group, whereas these two groups did not possess significant differences in recurrence-free survival." (PMID 37059993, 2023). "Knockout and rescue experiments revealed that the CLDN4 signaling targets the AKT phosphorylation site S432 in LXRβ, leading to enhanced cell proliferation, migration, and tumor growth, as well as cholesterol homeostasis and fatty acid metabolism, in breast cancer cells." (PMID 37059993, 2023). "Furthermore, loss of or decrease in CLDN4 expression in grade 1 IDCs and the absence of CLDN4 in special-type breast carcinomas and in areas of apocrine metaplasia in benign breast tissue, as compared with normal epithelium, suggest a role for CLDN4 in cellular differentiation." (PMID 15743508, 2005). "Negative carcinoma markers such as claudin-4, MOC-31, Ber-EP4, and CEA are used to exclude metastatic adenocarcinoma, particularly lung or breast carcinoma." (PMID 41517292, 2025). "Together, these results indicated that CLDN4 is a direct GRHL2 target while CDH1, ZEB1, or ZEB2 are unlikely to represent direct GRHL2 target genes in luminal breast cancer cells." (PMID 36691073, 2023). "Using this approach we determined that claudin-low breast cancer is typically negative for ER, PR, HER2, claudin 3, claudin 4, claudin 7 and E-cadherin." (PMID 28045912, 2017). "Both RJ348 and RJ423 cells expressed only extremely low levels of Cldn3, Cldn4 and Cldn7 (data not shown) suggesting that both RJ348 and RJ423 cells share features of human claudin-low breast cancers." (PMID 28423599, 2017).